TNFAIP8 (TNF alpha induced protein 8)
Description:
Acts as a negative mediator of apoptosis and may play a role in tumor progression. Suppresses the TNF-mediated apoptosis by inhibiting caspase-8 activity but not the processing of procaspase-8, subsequently resulting in inhibition of BID cleavage and caspase-3 activation.
Synonyms: NDED; GG2-1; MDC-3.13; SCC-S2; SCCS2
Tractability: PROTAC: ubiquitination databases record sites on it; its protein half-life has been measured.
Gene: Protein-coding gene on chromosome 5 (119,268,692 to 119,399,688, forward strand). Ensembl gene ENSG00000145779.
Subcellular location: Cytoplasm
Subcellular location (Human Protein Atlas): Nucleoplasm
Pathways (Reactome):
Metabolism: PI Metabolism
Gene Ontology:
Molecular function: cysteine-type endopeptidase inhibitor activity involved in apoptotic process; protein binding
Biological process: positive regulation of apoptotic process; negative regulation of apoptotic process; regulation of intracellular signal transduction; regulation of apoptotic process
Cellular component: cytoplasm; nucleoplasm
Genetic constraint (gnomAD): Loss-of-function variants: 7 observed, 10.39 expected, observed/expected ratio (o/e) 0.67, 90% interval 0.38 to 1.26. The upper end of that interval is the gene's LOEUF score, 1.26, which puts it in group 5 of 6, group 1 being the genes least tolerant of losing a copy. Missense variants: 258 observed, 240.62 expected, observed/expected ratio (o/e) 1.07, 90% interval 0.97 to 1.19. Synonymous variants: 94 observed, 90 expected, observed/expected ratio (o/e) 1.04, 90% interval 0.88 to 1.24.
Homologues: Orthologues: chimpanzee TNFAIP8 (96% identical), pig TNFAIP8 (96% identical), dog TNFAIP8 (93% identical), rat Tnfaip8 (93% identical), guinea pig TNFAIP8 (93% identical), mouse Tnfaip8 (89% identical), tropical clawed frog tnfaip8 (84% identical), Drosophila melanogaster sigmar (39% identical). Paralogues in human: TIPE3 (58% identical), TIPE1 (53% identical), TIPE2 (50% identical).
Diseases named in the same sentence as TNFAIP8 in open-access papers:
TNFAIP8 is named in the same sentence as 77 diseases in open-access papers, as found by Europe PMC text mining. Sharing a sentence is not in itself a finding about the gene and the disease. The quoted sentences say what the papers report.
breast cancer (16 papers, 2012 to 2024). A primary or metastatic malignant neoplasm involving the breast. "Furthermore, we identify TNFAIP8 as a tumor-promoter that are required for several hallmark traits of breast cancer cells, such as maintenance of proliferative signaling and promotions of lymph node metastasis." (PMID 32514245, 2020). "Collectively, these data suggest that TNFAIP8 expression may be associated with higher autophagic flux in MCF10A breast epithelial cells compared with MCF-7 breast cancer cells." (PMID 29928491, 2018). "Elevated expression levels of both lncRNA H19 and TNFAIP8 are observed in breast cancer tissues and cell lines, particularly in TNBC." (PMID 39479021, 2024). "TNFAIP8 and NRIP1 are mostly associated with tumors, with breast cancer appearing more frequently in our GD network." (PMID 37026010, 2023). "The expression of TNFAIP8 (also known as SCC-S2) has been found to be greater in invasive ductal breast carcinoma (BRCA) than in the adjacent tissues, suggesting that TNFAIP8 promotes the growth and migration of breast cancer cells." (PMID 36118167, 2022). "The exogenous expression of TNFAIP8 promoted proliferation and migration in breast cancer both in vitro and in vivo." (PMID 34925463, 2021). "Higher levels of TNFAIP8 protein expression were found in human breast cancer and renal cell carcinoma tissues than in matched normal adjacent tissues." (PMID 34925463, 2021). "Head and neck squamous cell carcinoma, esophageal squamous cell carcinoma, breast cancer, and non-small cell lung carcinoma show an increased expression of TNFAIP8 mRNA." (PMID 32986381, 2020). "The expression of lncRNA H19 and TNFAIP8 was up-regulated in breast cancer tissues and cell lines, especially in triple-negative breast cancer (TNBC)." (PMID 32514245, 2020). "We first determined the expression of lncRNA H19 and TNFAIP8 in breast cancer tissues and cells by qRT-PCR and western blotting analysis." (PMID 32514245, 2020). "Taken together, these findings suggest that lncRNA H19 promoted cell growth and EMT process in breast cancer cells, possibly through the positive regulation of TNFAIP8." (PMID 32514245, 2020). "In the current study, we found that lncRNA H19 and TNFAIP8 were markedly enhanced in breast cancer tissues and cell lines, with TNBS cells in particular." (PMID 32514245, 2020). "Expression of TNFAIP8 in breast cancer cells MDA-MB-435 increases cell growth/metastasis and reduces cell apoptosis by increasing expression of VEGFR-2, MMP1, and MMP9." (PMID 31723944, 2019). "In this study, we investigated the role of TNFAIP8 in the regulation of cell-cycle-related proteins and autophagy in prostate and breast cancer cells." (PMID 29928491, 2018). "We investigated the role of TNFAIP8 in modulating the expression of cell-cycle-related proteins, autophagy biomarkers, and drug resistance in prostate and breast cancer cell lines." (PMID 29928491, 2018). "In order to establish the broader role of TNFAIP8 in autophagy modulation, we analyzed the expression of TNFAIP8 and LC3β I/II in normal and breast cancer cells by immunoblotting." (PMID 29928491, 2018). "The evaluation of a limited number of clinical specimens has revealed higher expression levels of TNFAIP8 protein in human breast cancer and RCC tissues compared with matched normal adjacent tissues." (PMID 24137373, 2013).
breast cancer (continued). "Increasing experimental evidences support that TNFAIP8 is an oncogene in human cancers, such as breast cancer and lung cancer." (PMID 24274578, 2013). "TNFAIP8 mRNA over-expression has been found in various malignant cell lines, such as breast cancer, non-small cell lung cancer, and esophageal squamous cell carcinoma." (PMID 22666399, 2012). "The exogenous expression of TNFAIP8 promoted proliferation and migration in breast cancer." (PMID 34925463, 2021). "Given that TNFAIP8 is overexpressed in breast cancer cells, we then wanted to determine whether inhibition of TNFAIP8 by siRNA in BT-549 and MDA-MB-231 cells could influence cell proliferation, migration, and invasion." (PMID 32514245, 2020). "In addition, lncRNA H19 altered the expression of cascades of EMT makers and promoted proliferation, migration and invasion of breast cancer cells through positive regulation of TNFAIP8." (PMID 32514245, 2020). "Moreover, the enhanced expression of lncRNA H19 and TNFAIP8 was also evident in serial breast cancer cell lines, particularly in TNBC cells." (PMID 32514245, 2020). "We also showed that TNFAIP8 modulates breast cancer cell progression." (PMID 30586922, 2018). "Similarly, high levels of TNFAIP8 expression in breast cancer, gastric cancer, pancreatic cancer, epithelial ovarian cancer and oesophageal squamous cell carcinoma correlates with tumour stage and lymph node metastasis and can predict poor survival." (PMID 30064446, 2018). "Interestingly, we also demonstrated that TNFAIP8-induced autophagy in prostate cancer and breast cancer cells leads to increased drug resistance and cell survival in prostate cancer cells." (PMID 30586922, 2018). "Collectively our results suggest that TNFAIP8 increases cellular autophagy in breast cancer cells." (PMID 29928491, 2018). "Overexpression of TNFAIP8 in MDA-MB-435 cells increases cell growth and tumorigenicity and enhances breast cancer cell migration by up-regulation of collagen I." (PMID 30586922, 2018). "Knockdown of TNFAIP8 reduced the expression of LC3β I/II in breast cancer MCF7 cells (data not shown) and prostate cancer PC3 cells, which reinforces the role of TNFAIP8 in LC3β I/II regulation and autophagy." (PMID 29928491, 2018).
lung cancer (9 papers, 2013 to 2021). A malignant neoplasm involving the lung. "Human TNFAIP8 gene encodes eight transcript variants/isoforms, whereas only five protein variants reported so far and TNFAIP8 variant two predominantly expressed in prostate, breast, liver, lung cancer cells, and acute monocytic leukemia derived THP1 cells compared to other variants." (PMID 31723944, 2019). "In addition, TNFAIP8 is also a risk factor for non-Hodgkin's lymphoma 37; high levels of TNFAIP8 expression are also associated with more aggressive epithelial ovarian cancer 38 and nonsmall cell lung cancer." (PMID 32226521, 2020). "In addition, the expression of TNFAIP8 in tumor-infiltrating CD8+ T cells in advanced lung cancer patients was lower than that in primary lung cancer patients, suggesting that the loss of TNFAIP8 may be involved in the progression of non–small-cell lung cancer." (PMID 34925463, 2021). "The molecular mechanistic role of TNFAIP8 in the regulation of Hippo signaling by interaction with LATS1 is reported in lung cancer cells." (PMID 30586922, 2018). "Similar to lung cancer cells TNFAIP8 modulates the Hippo pathway in liver cancer cells by inhibition of YAP phosphorylation and by interaction with LATS1." (PMID 30586922, 2018). "In lung cancer, TNFAIP8 mRNA levels are higher in cancer tissues compared with healthy lung tissue donors." (PMID 30586922, 2018). "Western blot analyses were performed to measure the TNFAIP8 protein levels in the lung cancer cell lines examined." (PMID 30064446, 2018). "In this study, we analysed clinical NSCLC samples and determined that increased TNFAIP8 immunoreactivity in lung cancer patients was accompanied by decreased postoperative survival." (PMID 30064446, 2018). "We first performed gene expression profiling in lung cancer cells after shRNA knockdown of TNFAIP8 and analysed the gene expression data." (PMID 30064446, 2018). "TNFAIP8 interacts with LATS1 and decreases LATS1 phosphorylation, which leads to increased nuclear localization of YAP protein, resulting in increased lung cancer cell proliferation and invasion." (PMID 30586922, 2018). "In addition, in patients with advanced stages of lung cancer, the expression of TNFAIP8 in tumor-infiltrating CD8+ T cells is lower compared to patients with primary stages of lung cancer, suggesting that TNFAIP8 may be involved in the progression of non-small cell lung cancer (NSCLC)." (PMID 30586922, 2018).
head and neck squamous cell carcinoma (7 papers, 2015 to 2021). A squamous cell carcinoma that arises from any of the following anatomic sites: lip and oral cavity, nasal cavity, paranasal sinuses, pharynx, larynx, and salivary glands. "Human TNFAIP8 was first identified through comparison of primary and metastatic head and neck squamous cell carcinoma, and later TNFAIP8 was identified from endothelial cells as a TNFα inducible gene." (PMID 31723944, 2019). "TNFAIP8 was first found in primary human head and neck squamous cell carcinoma (HNSCC) cell line and its matched metastatic cell line which were from the same patient through analysis of the expression profile." (PMID 31043860, 2019). "TNFAIP8, also known as SCC-S2, has been identified in human head and neck squamous cell carcinoma (HNSCC)." (PMID 28152516, 2017). "Tumor necrosis factor-α–induced protein 8 (TNFAIP8) is a member of the TIPE/TNFAIP8 family, which was first found in human head and neck squamous cell carcinoma, and play important roles in immunity, oncogenesis, and tumor progression." (PMID 34925463, 2021). "Tumor necrosis factor α-induced protein 8 (TNFAIP8), also called SCC-S2, GG2-1, MDC-3.13, NDED and OXI-α, containing a death effector domain, was first found in human head and neck squamous cell carcinoma." (PMID 32795319, 2020). "Tumor necrosis factor α-induced protein 8 (TNFAIP8), the first member of TNFAIP8 family, was originally identified by comparing two primary and two matched metastatic head and neck squamous cell carcinoma (HNSCC) cell lines using the methods of northern blot and differential display of mRNAs." (PMID 26207809, 2015).
endometrial cancer (6 papers, 2017 to 2020). Primary or metastatic malignant neoplasm involving the endometrium (mucous membrane that lines the endometrial cavity). "Furthermore, the study of endometrial cancer (EC) showed that the GG genotype and AG + GG genotype of TNFAIP8 rs11064 were both associated with increased risk compared with controls." (PMID 32821249, 2020). "Tumor necrosis factor-a-induced protein 8 (TNFAIP8) presented a elevated expression in endometrial cancer (EC)." (PMID 31043860, 2019). "TNFAIP8 has been demonstrated to be upregulated in gastric adenocarcinoma tissues, platinum-resistant epithelial ovarian cancer tissues, endometrial cancer tissues and NSCLC tumor tissues." (PMID 29108244, 2017). "In TNFAIP8 upregulated endometrial cancer tissues, higher histologic grade, deeper myometrial invasion and lymph vascular space invasion and more lymph node metastasis were found, companied with poor overall survival and disease-free survival (DFS) rates." (PMID 29108244, 2017). "TNFAIP8 expression strongly correlates with MMP9 and Ki-67 expression, suggesting that TNFAIP8 may be used as a prognostic marker for the recurrence of endometrial cancers." (PMID 30586922, 2018). "Similarly, in endometrial cancers, the expression of TNFAIP8 in tumor specimens is positively correlated with clinicopathologic factors such as higher histologic grade, deep myometrial invasion, lymphovascular space invasion, lymph node metastasis, and recurrence." (PMID 30586922, 2018).
gastric cancer (6 papers, 2015 to 2021). A primary or metastatic malignant neoplasm involving the stomach. "Collectively, these findings indicated that TNFAIP8 was associated with gastric cancer and can be considered as an oncogene." (PMID 25936980, 2015). "The expression of TNFAIP8 was significantly upregulated in the gastric cancer tissues and in the gastric cancer cell lines, and its expression levels were associated with the TNM staging and lymphatic metastasis." (PMID 25936980, 2015). "In a recent study, TNFAIP8 has been associated with the tumorigenicity of gastric cancer." (PMID 32883271, 2020). "However, prior to the present study, the expression of TNFAIP8 and its functions associated with gastric cancer remained to be elucidated." (PMID 25936980, 2015). "In the present study, we investigated the relationship between the TNFAIP8 and the mTOR‐Akt‐ULK1signalling pathway as well as its role in gastric cancer." (PMID 33682317, 2021). "This suggested that TNFAIP8 can be used as a sole prognostic value for metastasis and is expected to become a potential target for the treatment of gastric cancer." (PMID 25936980, 2015). "In the present study, the cell invasion and migration assay demonstrated that TNFAIP8 knockdown inhibited cell invasion and migration in the two types of gastric cancer cells." (PMID 25936980, 2015). "Taken together, these data suggested that TNFAIP8 was involved in promoting the progression of gastric cancer." (PMID 25936980, 2015). "The expression of TNFAIP8 and its association with the tumor, node, metastasis (TNM) status and lymphatic metastasis of gastric cancer was evaluated." (PMID 25936980, 2015). "Tumor necrosis factor α-induced protein 8 (TNFAIP8) has been associated with the tumorigenicity of various types of cancer, however, the expression of TNFAIP8 and its function in gastric cancer remain to be fully elucidated." (PMID 25936980, 2015). "Despite the requirement for further investigations to confirm and develop this IHC data, these results revealed that TNFAIP8 was commonly enhanced in gastric cancer tissues, compared with normal tissues or deeper invasion tissues." (PMID 25936980, 2015). "In the present study, the expression of TNFAIP8 in gastric cancer was detected using immunofluorescence to confirm its cytoplasmic localization." (PMID 25936980, 2015). "The overexpression of TNFAIP8 protein in gastric carcinoma tissues compared with normal tissues was demonstrated, which was in accordance with the results of a previous study." (PMID 25936980, 2015). "In conclusion, the results of the present study indicated that the protein and mRNA expression levels of TNFAIP8 in gastric carcinoma tissues and cells were significantly higher compared with those in normal tissues and cells." (PMID 25936980, 2015). "The expression levels of TNFAIP8 in the gastric carcinoma cells were significantly higher compared with those in the GES-1 cells." (PMID 25936980, 2015). "The decreased expression of TNFAIP8 inhibits the growth, invasion and migration of gastric cancer." (PMID 32883271, 2020). "Therefore, the present study examined the expression and biological function of TNFAIP8 in gastric cancer." (PMID 25936980, 2015). "Furthermore, the four gastric cancer cell lines exhibited higher expression levels of TNFAIP8 than the GES-1 cells, and the SGC-7901 and MKN-28 cells exhibited relatively high levels of expression in the four cancer cell lines." (PMID 25936980, 2015). "Furthermore, decreased expression of TNFAIP8 inhibited the growth, invasion and migration of gastric cancer cells." (PMID 25936980, 2015). "Furthermore, the functions of decreased expression levels of TNFAIP8 were analyzed in human gastric cancer cell lines." (PMID 25936980, 2015).